HSD11B2 (hydroxysteroid 11-beta dehydrogenase 2)
Description:
Catalyzes the conversion of biologically active 11beta-hydroxyglucocorticoids (11beta-hydroxysteroid) such as cortisol, to inactive 11-ketoglucocorticoids (11-oxosteroid) such as cortisone, in the presence of NAD(+). Functions as a dehydrogenase (oxidase), thereby decreasing the concentration of active glucocorticoids, thus protecting the nonselective mineralocorticoid receptor from occupation by glucocorticoids. Plays an important role in maintaining glucocorticoids balance during preimplantation and protects the fetus from excessive maternal corticosterone exposure (By similarity). Catalyzes the oxidation of 11beta-hydroxytestosterone (11beta,17beta-dihydroxyandrost-4-ene-3-one) to 11-ketotestosterone (17beta-hydroxyandrost-4-ene-3,11-dione), a major bioactive androgen. Catalyzes the conversion of 11beta-hydroxyandrostenedione (11beta-hydroxyandrost-4-ene-3,17-dione) to 11-ketoandrostenedione (androst-4-ene-3,11,17-trione), which can be further metabolized to 11-ketotestosterone. Converts 7-beta-25-dihydroxycholesterol to 7-oxo-25-hydroxycholesterol in vitro. 7-beta-25-dihydroxycholesterol (not 7-oxo-25-hydroxycholesterol) acts as a ligand for the G protein-coupled receptor (GPCR) Epstein-Barr virus-induced gene 2 (EBI2) and may thereby regulate immune cell migration. May protect ovulating oocytes and fertilizing spermatozoa from the adverse effects of cortisol (By similarity). Catalyzes the conversion of 7-beta-hydroxycholesterol into 7-ketocholesterol (7-oxocholesterol), a precursor of 7-keto,27-hydroxycholesterol, which activates smoothened (SMO) and the smoothened signaling pathway (By similarity).
Synonyms: HSD11K; SDR9C3; AME; AME1; HSD2
Tractability: Small molecule: an approved drug acts on it; a high-quality ligand is known; it belongs to a druggable protein family. PROTAC: a small molecule that binds it is known.
Target class: Enzyme; Oxidoreductase
Chemical probes: CHEMBL1269273, CHEMBL1689279
Gene: Protein-coding gene on chromosome 16 (67,430,652 to 67,437,553, forward strand). Ensembl gene ENSG00000176387.
Subcellular location: Microsome; Endoplasmic reticulum
Subcellular location (Human Protein Atlas): Vesicles
Pathways (Reactome):
Drug ADME: Prednisone ADME
Metabolism: Glucocorticoid biosynthesis
Gene Ontology:
Molecular function: 11-beta-hydroxysteroid dehydrogenase (NAD+) activity; 7-beta-hydroxysteroid dehydrogenase (NADP+) activity; NAD binding; oxidoreductase activity, acting on the CH-OH group of donors, NAD or NADP as acceptor; steroid binding
Biological process: cortisol metabolic process; glucocorticoid metabolic process; positive regulation of smoothened signaling pathway; female pregnancy; regulation of blood volume by renal aldosterone; response to food; response to glucocorticoid; response to hypoxia; response to insulin; response to steroid hormone; response to xenobiotic stimulus
Cellular component: endoplasmic reticulum membrane; endoplasmic reticulum
Genetic constraint (gnomAD): Loss-of-function variants: 22 observed, 26.08 expected, observed/expected ratio (o/e) 0.84, 90% interval 0.6 to 1.2. The upper end of that interval is the gene's LOEUF score, 1.2, which puts it in group 5 of 6, group 1 being the genes least tolerant of losing a copy. Missense variants: 480 observed, 515.51 expected, observed/expected ratio (o/e) 0.93, 90% interval 0.86 to 1. Synonymous variants: 253 observed, 226.81 expected, observed/expected ratio (o/e) 1.12, 90% interval 1.01 to 1.24.
Gene-disease validity (ClinGen):
ClinGen rates the evidence that HSD11B2 causes each of these diseases.
apparent mineralocorticoid excess (autosomal recessive): Definitive. Apparent mineralocorticoid excess (AME) is a rare form of pseudohyperaldosteronism characterized by very early-onset and severe hypertension, associated with low renin levels and hypoaldosteronism.
Homologues: Orthologues: chimpanzee HSD11B2 (100% identical), macaque HSD11B2 (99% identical), dog HSD11B2 (90% identical), rat Hsd11b2 (86% identical), mouse Hsd11b2 (82% identical), pig HSD11B2 (82% identical), guinea pig HSD11B2 (80% identical), rabbit HSD11B2 (71% identical), tropical clawed frog hsd11b2 (44% identical), zebrafish hsd11b2 (43% identical). Paralogues in human: HSD17B2 (35% identical), RDH16 (25% identical), HSD17B6 (25% identical), RDH5 (24% identical), DHRS9 (23% identical), SDR9C7 (23% identical), BDH1 (22% identical), HSD17B1 (19% identical), RDH12 (18% identical), RDH11 (17% identical), HSD17B4 (16% identical), SDR16C5 (16% identical), and 13 more.
Diseases named in the same sentence as HSD11B2 in open-access papers:
HSD11B2 is named in the same sentence as 67 diseases in open-access papers, as found by Europe PMC text mining. Sharing a sentence is not in itself a finding about the gene and the disease. The quoted sentences say what the papers report.
Hypertension (33 papers, 2008 to 2025). The presence of chronic increased pressure in the systemic arterial system. "Kidney-specific gene deletion of HSD11B2, which induces human or renal dysfunction, causes hypertension." (PMID 39125667, 2024). "Hypermethylation of the HSD11B2 gene promoter led to increased activity of the 11-betaHSD2 enzyme and the risk of hypertension." (PMID 36551003, 2022). "As well as genetic deficiencies, epigenetic modifications also play a crucial role in regulating HSD11B2 expression in the onset of hypertension with underlying defects in 11β-HSD2." (PMID 36329487, 2022). "Similar findings were reported in newborn babies whereby hypermethylation of the (HSD11B2) promoter gene was linked to a high risk of essential hypertension." (PMID 35668933, 2022). "One such gene 11-Betahydroxysteroid dehydrogenase type-2 (HSD11B2), performed in a rat model demonstrated a positive association between hypermethylation and hypertension." (PMID 35668933, 2022). "We report novel compound heterozygous HSD11B2 mutations in a Chinese teenager with early-onset hypertension, and enriched genotypic and phenotypic spectrums in AME." (PMID 32816205, 2020). "In mice, mutation of the HSD11B2 gene leads to hypertension, and increased anxiety-like behavior in adulthood, suggesting the regulation of placental 11ß–HSD2 function is central, linking antenatal stress with offspring morbidity long after birth." (PMID 32752005, 2020). "A systematic review of 101 AME patients with 54 HSD11B2 mutations revealed early-onset hypertension, hypokalemia and homozygous mutations as common features." (PMID 32816205, 2020). "High methylation levels of the HSD11B2 promoter are associated with increased blood pressure and is one of the factors influencing the onset of hypertension." (PMID 33569358, 2020). "Inhibition of HSD11B2 causes mineralocorticoid excess and hypertension due to inappropriate glucocorticoid activation of renal mineralocorticoid receptors." (PMID 31139205, 2019). "Several of them (Ace, Comt, Cyp1a1, Glp1r, Hsd11b2, and Ren) are widely known as associated with hypertension development." (PMID 26821914, 2016). "Human cell line studies have demonstrated that p.R337C mutation leads to the low activity of HSD11B2 due to reduced enzyme stability and causes low-renin hypertension thus resulting in AME9." (PMID 29067160, 2016). "Genetically null mutations of the HSD11B2 gene in the human cause a syndrome named apparent mineralocorticoid excess in which circulatory aldosterone levels are subnormal and are related to hypertension and hypokalemia." (PMID 26798634, 2015). "Carrying a mutation in HSD11B2 is, conversely, a genetic risk factor for licorice-induced hypertension or AME state." (PMID 20007258, 2011). "In conclusion, licorice ingestion is an environmental risk factor for hypertension or AME state in patients with a mutation in HSD11B2." (PMID 20007258, 2011). "Apparent mineralocorticoid excess (AME) is a rare autosomal recessive disorder caused by biallelic inactivating variants in the HSD11B2 gene resulting in hypertension and electrolyte abnormalities due to cortisol-mediated activation of mineralocorticoid receptors." (PMID 41316338, 2025). "HSD11B2 mutations lead to a deficiency in the 11βHSD2 enzyme, resulting in excessive cortisol stimulating the MR and causing intense water and sodium retention, hypokalemia, and hypertension." (PMID 32816205, 2020). "The discussion of ten of them known as associated with hypertension demonstrated that four of these genes (Avpr1a, Hsd11b2, Agt, Ephx2) may provoke the hypertension development, and Mpo may contribute to insulin resistance and inflammation in ISIAH rats." (PMID 28105924, 2016). "Indeed, null mutation of the HSD11B2 or pharmacological inhibition by chemicals has shown that mineralocorticoid receptors in the kidney are occupied by cortisol, causing apparent mineralocorticoid excess associated in part with hypertension and hypokalemia." (PMID 26798634, 2015).
Hypertension (continued). "Deficiency of HSD11B2, the gene encoding 11β-HSD2, causes apparent mineralocorticoid excess syndrome, a Mendelian hypertensive disorder." (PMID 38165850, 2024). "At baseline, when the two patients were free from specific therapy, with a florid disease characterized by low-renin, low-aldosterone hypokalemic hypertension, we observed a high exosomal HSD11B2 mRNA expression." (PMID 34497581, 2021). "In a study performed in patients with essential hypertension or glucocorticoid-induced hypertension, the HSD11B2 promoter was highly methylated." (PMID 31649728, 2019). "It was found that decreased HSD11B2 activity is related to hypertension and Hsd11b2 null mice are also hypertensive." (PMID 26821914, 2016). "Exosomal mRNA is a useful tool to investigate HSD11B2 dysregulation in hypertension." (PMID 34497581, 2021). "However, conditional Hsd11b2 knockout in the brain showed that increased salt appetite leads to hypertension." (PMID 34028587, 2021). "Some authors hypothesized the usefulness of detecting HSD11B2 or even other exosomal mRNAs for the study of the pathophysiological mechanisms of hypertensive diseases and in particular for the diagnosis of mineralocorticoid hypertension." (PMID 34497581, 2021). "Low activity of the 11 beta-hydroxysteroid dehydrogenase 2 (HSD11B2) induces hypertension." (PMID 31649728, 2019). "Four of them (Avpr1a, Hsd11b2, Agt, Ephx2) may provoke the hypertension development, and Mpo may contribute to insulin resistance and inflammation in the ISIAH rats." (PMID 28105924, 2016). "However, a partial deficit in the activity of the enzyme 11b-HSD2 was observed in essential hypertensive patients and a significantly lower level messenger RNA for HSD11B2 was found in the hypertensive patients." (PMID 25200528, 2014). "Moreover, animal model observed that basal blood pressure of brain-specific HSD11B2 knockout mice was similar to that of healthy control mice, but they gradually went on to develop hypertension for a three- fold increased salt consumption that could be inhibited by spironolactone." (PMID 36329487, 2022). "In addition, as a close relationship between UFF/UFEE ratio and hypertension, in both menopausal women and CS, has been described in previous studies, we hypothesized the role of HSD11B2 activity (evaluated by the UFF/UFE ratio) in determining surgical outcomes." (PMID 35721734, 2022). "Multiple lines of evidence show that the higher the degree of HSD11B2 promoter methylation, the lower the activity of 11β-HSD2, which possibly explains the inconsistent phenotype of hypertension among AME patients." (PMID 33569358, 2020). "It is unknown whether urinary exosomal HSD11B2 mRNA is related to steroid ratio or the HSD11B2 662 C>G genotype (corresponding to a 221 A>G substitution) in patients with AME and essential hypertension (EH)." (PMID 34497581, 2021). "The results highlight, moreover, that the urinary exosomal HSD11B2 mRNA expression varies according to the HSD11B2 662C>G genotype in an AME family, suggesting a potential use of it as a molecular marker of hypertensive disease, due to an impaired 11β-HSD2 enzyme function." (PMID 34497581, 2021). "In this study, we demonstrated that licorice ingestion can produce overt hypertension in an individual without medical history of hypertension who is heterozygous for wild-type and mutant HSD11B2 genes." (PMID 20007258, 2011).
Anxiety (10 papers, 2012 to 2023). Intense feelings of nervousness, tension, or panic often arise in response to interpersonal stresses. "Animal models have also linked reduced HSD11B2 gene expression to adverse neurobehavioral outcomes including increased anxiety and stress in adult rodents." (PMID 22432047, 2012). "Furthermore, these studies suggest that the association between maternal anxiety or stress and placental HSD11B2 is specific to maternal distress during late pregnancy." (PMID 26593902, 2015). "Furthermore, maternal anxiety and depression measured in late gestation displayed stronger associations with placental HSD11B2 expression levels than maternal depression and anxiety in early pregnancy (12–18 weeks)." (PMID 26593902, 2015). "Furthermore, associations between placental HSD11B2 and scores on the State-Trait Anxiety Inventory (STAI) and Edinburgh Postnatal Depression Scale (EPDS) during 12–18 and 28–34 weeks gestation were examined." (PMID 26593902, 2015). "Thus, it is possible that human research also lends support to the idea that downregulation of HSD11B2 expression is related to chronic depression or anxiety and upregulation is associated with acute distress." (PMID 26593902, 2015). "In mice, mutation of the HSD11B2 gene leads to hypertension, excess mineralocorticoid activity, and increased anxiety-like behavior in adulthood whereas HSD11B1 mutation leads to attenuated negative-feedback of the HPA response to stress and improved cognitive performance in aging." (PMID 22761903, 2012). "The methylation of the placental HSD11B2 concurs with a dysfunctional neurobehavior among newborns born from mothers suffering from antenatal depression or anxiety." (PMID 32752005, 2020). "Placental HSD11B2 has been shown to be reduced in a number of adverse pregnancy conditions including anxiety, stress, and infection." (PMID 28321257, 2017). "This study examined the effect of maternal depressive disorder, antidepressant use and symptoms of depression and anxiety in pregnancy on placental 11β-HSD2 gene (HSD11B2) expression." (PMID 26593902, 2015). "The current study aimed to investigate the effect of maternal depressive disorders, symptoms of maternal anxiety and depression across pregnancy on HSD11B2 expression levels." (PMID 26593902, 2015). "Those bred for high anxiety had significantly lower placental HSD11B2 expression levels than the low anxiety group." (PMID 26593902, 2015). "Furthermore, only boys showed differential methylation of the FKBP5 gene in response to prenatal pregnancy-related anxiety; also, methylation of NR3C1 and HSD11B2 genes was associated with the risk of emotional symptoms and hyperactivity only in boys." (PMID 34715840, 2021). "We hypothesized that exposure to maternal pregnancy-related anxiety in utero may program child gender-specific neurobehavior via gender-specific DNA methylation of HSD11B2, NR3C1 and FKBP5 genes in placenta." (PMID 34715840, 2021). "As second trimester anxiety was associated with female birth weight, we next examined the relationship between second trimester STAI scores and three key genes involved in glucocorticoid signalling in the placenta, HSD11B2, NR3C1 and FKBP51." (PMID 30310158, 2018). "In relation to the strength of their association with HSD11B2, results indicated that maternal trait and state anxiety in both Trimester 1 and 3 did not significantly differ from each other." (PMID 26593902, 2015). "In support of HSD11B2 expression mediating the relationship between maternal distress and infant outcomes, a recent study selectively bred Wistar rats for high anxiety-related behaviour or low anxiety-related behaviour and exposed both groups to identical stressors." (PMID 26593902, 2015). "In doing so, the study also intended to determine whether maternal anxiety or depression symptoms have different effects on HSD11B2 expression." (PMID 26593902, 2015).
Anxiety (continued). "Women with perceived symptoms of anxiety and depression during pregnancy had altered expression patterns for CRH, HSD11B2, and AVP genes in the placentas, compared to the control population." (PMID 32752005, 2020). "However to date, no human study has differentiated between the effects of acute, chronic, mild or severe depression or anxiety on HSD11B2 expression, and greater research investigating the effect of distress severity and chronicity on HSD11B2 is needed to test the suggested hypotheses." (PMID 26593902, 2015). "However, since animal research suggests that placental HSD11B2 may be influenced by gestation and the chronicity of maternal distress, it is possible that the episodic nature of prenatal depression and anxiety also has an influence on the expression of placental HSD11B2." (PMID 26593902, 2015). "Pearson correlations showed negative relationships between HSD11B2 expression and measures of anxiety (STAI-T, STAI-S) in the first and third trimesters of pregnancy." (PMID 26593902, 2015). "However, the scores of the factor characterized by FKBP5, NR3C1 and HSD11B2 did not mediate the relationship between maternal pregnancy-related anxiety and preschoolers’ emotional symptoms and hyperactivity." (PMID 34715840, 2021). "Correlations between HSD11B2 expression and changes in scores on the EPDS and STAI-S (state anxiety) between the first and third trimester suggested negative relationships, while the correlation between HSD11B2 and changes in STAI-T (trait anxiety) remained positive." (PMID 26593902, 2015). "Likewise, changes in self-reported maternal state anxiety and depressive symptoms from Trimester 1 to 3 were negatively related to HSD11B2, where improvements in maternal mental health (lower EPDS and STAI scores) led to higher placental HSD11B2 expression levels." (PMID 26593902, 2015).
mineralocorticoid excess (10 papers, 2015 to 2026). "Apparent mineralocorticoid excess (AME) is a rare autosomal recessive disorder caused by loss-of-function mutations in HSD11B2, leading to impaired conversion of cortisol to cortisone and inappropriate mineralocorticoid receptor activation." (PMID 42064719, 2026). "The syndrome of apparent mineralocorticoid excess is caused by deficiency of 11β-hydroxysteroid dehydrogenase type 2 (Hsd11b2), which normally inactivates glucocorticoids, rendering the mineralocorticoid receptor aldosterone–specific." (PMID 26077568, 2015). "We investigated early sodium and water handling in neonates from a second rat strain, Fischer, and an Hsd11b2-knockout rat modelling the syndrome of apparent mineralocorticoid excess (SAME)." (PMID 34028587, 2021). "Apparent mineralocorticoid excess (AME, #OMIM 614232), also known as cortisol 11β- hydroxysteroid deshydrogenase deficiency, is an autosomal recessive disorder caused by mutations in the 11β-hydroxysteroid dehydrogenase type 2 (HSD11B2) gene." (PMID 39931437, 2024).
depression (7 papers, 2012 to 2021). "Smoking and depression in pregnancy have also been associated with altered methylation of placental stress-related genes, such as NR3C1 and HSD11B2, which encodes the enzyme that inactivates cortisol." (PMID 33608499, 2021). "The results further indicate that women with untreated major depression and those using antidepressants have markedly lower placental HSD11B2 expression levels than controls." (PMID 26593902, 2015). "First, we found negative associations between HSD11B2 expression and self-reported maternal anxiety and depression." (PMID 26593902, 2015). "An ANCOVA controlling for BMI, smoking and alcohol consumption revealed that group status (antidepressant exposure, untreated depression and controls) accounted for 5.9% of HSD11B2 expression (F = 0.84, p = 0.44, n = 33) instead of 7.1% (the computed effect size without consideration of covariates)." (PMID 26593902, 2015).